S100A8 (S100 calcium binding protein A8)
Diseases named in the same sentence as S100A8 in open-access papers (continued):
Sharing a sentence is not in itself a finding about the gene and the disease.
cancer (continued). "In addition to transcription factors, in AML samples, we identified the upregulation of genes that were reported to accelerate leukaemogenesis, including S100A8, S100A9, and RPS26, and the downregulation of genes related to cancer control and defence, such as XIST, GIMAP7, NKG7, and GNLY." (PMID 37615858, 2024). "Importantly, earlier generations of S100A8/A9 blockers including laquinimod (ABR-215062), tasquinimod (ABR-215050) and paquinimod (ABR-215757), have been or are currently undergoing clinical testing for treatment of inflammatory diseases and cancer." (PMID 37773186, 2023). "However, limited studies have focused on the significance of S100A8 and TME in cancer based on the current excellent design approach, and we aimed to use bioinformatics to explore SAS100A8 expression in 33 different malignant tumors and its potential effect on immune TME." (PMID 35646116, 2022). "CXCL1, LCN2, S100A8, and IDO1 may play essential roles in cancer progression." (PMID 34306038, 2021). "Our data suggests that S100A8/A9 upregulation in non-tumorigenic mammary epithelial cells may play a critical role in the phenotype shifting induced by adjacent cancer cells." (PMID 33446797, 2021). "At high intracellular concentrations, S100A8/A9 does not affect the apoptosis pathway instead by regulating the epithelial–mesenchymal transition and the mesenchymal–epithelial transitions inducing a reduction in cancer cell invasion capacity." (PMID 33567747, 2021). "Six of these proteins had a higher abundance in cancer patients than in healthy controls (RNF213/ring finger protein 213; CTSG/cathepsin G; PGLYRP1/peptidoglycan recognition protein 1; RPL8/ribosomal protein L8; S100A8/S100 calcium binding protein A8; S100A9/S100 calcium binding protein A9)." (PMID 34361002, 2021). "Moreover, anti-inflammatory TAMs induce S100A8 and S100A9 expression on HCC cancer cells, release CCL22 and epidermal growth factor (EGF) to recruit Treg cells, and promote migration of tumor cells, altogether contributing to HCC malignancy and liver metastasis." (PMID 31611871, 2019). "Inhibition of S100A8 and S100A9 activity may have significant implications in cancer chemotherapy." (PMID 29955397, 2018). "Moreover, increased expression of S100A8 mediated the activation of MAPK and NF-κB pathways, and treatment with p38 MAPK inhibitor SB203580 and the NF-κB inhibitor Bay 11-7082 effectively abolished migration and invasion of cancer cells." (PMID 28183295, 2017). "As is the case for TGFβ1, the calcium binding proteins S100A8/A9 are dual faced molecules that are not only involved in PDAC growth and dissemination, but can also form complexes with TGFβ1 thus concurring in further enhancing the spectrum of the effects evoked in cancer cells by this cytokine." (PMID 27655713, 2016). "S100A8 and S100A9, members of the S100 proteins, are small calcium-binding proteins that are highly expressed in neutrophil and monocyte cytosol and are found to be overexpressed during inflammatory conditions and in some types of cancer such as pancreatic, colorectal, and gastric cancer." (PMID 26273651, 2015). "To determine whether S100A8/A9 suppressed carcinoma cell growth by regulating cell cycle, we performed cell cycle analysis in S100A8/A9-expressing and non-expressing KB cells." (PMID 23874958, 2013). "As the enhanced level of S100A8 and S100A9 proteins is a characteristic feature of numerous inflammatory, cancers and degenerative conditions taking place in different tissues and organs, they may effectively contribute to the disease pathologies also via amyloid depositions." (PMID 22489132, 2012). "Thus, we investigated whether tissue S100A8/A9 expression in the absence of cancer cells can induce 18F-FDG-uptake." (PMID 32170086, 2020). "In contrast, S100A8 treatment decreased percentage of NK cells and their absolute numbers in lungs of mice with LLC cancers (CD3-/NK1.1+) (12.6 ± 1.0% to 6.7 ± 0.5%, p < 0.001); no change was observed in the spleen." (PMID 35655772, 2022).
cancer (continued). "S100A8 and S100A9 are involved in numerous inflammation and carcinogenesis cellular processes and can be used as cancer biomarkers, but are not specific markers for ovarian cancer." (PMID 23557354, 2013). "Notably, S100A8 and ALDH3A1 did not demonstrate statistical significance in our data, despite the publication reporting a notable decrease in cancer incidence." (PMID 37553345, 2023). "Although researchers focused on the roles of S100A8/S100A9 in inflammatory cells currently, there is also growing evidence for important roles of both proteins in non-myeloid cells, such as skin cells and cancer cells." (PMID 31208368, 2019). "The mechanisms mediating S100A8 and S100A9 regulation of MMP2 and MMP9 expression in cancer cells are not yet known but may involve their calcium-binding activity." (PMID 27086923, 2016). "Overall, we validated the consistency of up-regulation of the four proteins (COL12A1, THBS2, S100A8, and S100A9) was only observed in CRC but not in other cancer types; and the four proteins could achieve good performance in the diagnosis of CRC, but not other cancer types." (PMID 38302471, 2024). "Next, we tested whether S100A8 treatment alone altered lymphocyte infiltration and found significantly increased percentage of total T cells (CD3+) (21.7 ± 2.9% to 34.4 ± 1.3%, p < 0.001) and their absolute numbers in lungs, but not in spleen, of cancer-bearing mice compared to controls." (PMID 35655772, 2022).
cardiovascular disease (41 papers, 2010 to 2025). "S100A8 has mainly been implicated in cardiovascular disease by promoting vascular endothelial cell dysfunction and apoptosis." (PMID 37623250, 2023). "Treatment with a miR-21 mimic significantly inhibited the expression of S100a8, an inflammation-associated protein that regulates the development of multiple cardiovascular diseases." (PMID 35907209, 2022). "This review explores S100A8/A9's utility as a diagnostic tool for cardiovascular system effects and as a marker for cardiovascular events, providing a theoretical basis for the clinical treatment of cardiovascular diseases." (PMID 39175627, 2024). "Fourth, S100A8 has mainly been implicated in cardiovascular disease." (PMID 37623250, 2023). "Additionally, S100A8 has been found to correlate with traditional cardiovascular risk factors and the manifestation of cardiovascular disease." (PMID 26792056, 2016). "This article provides a review of the impact of S100A8/A9 on cardiovascular diseases, from a mechanism point of view, to highlight its importance as a biomarker for cardiac injury." (PMID 39329929, 2024). "These methods collectively work to attenuate the pro-inflammatory and pro-oxidative effects of S100A8/A9, offering significant potential in the treatment of cardiovascular diseases." (PMID 39175627, 2024). "Looking ahead, with the advancement of research technologies, the S100A8/A9 protein is expected to become a new focus for the diagnosis and treatment of cardiovascular diseases, potentially revolutionizing clinical approaches to diagnosis and therapy." (PMID 39175627, 2024). "These therapeutic approaches aim to mitigate inflammation and oxidative stress by inhibiting the expression or function of S100A8/A9, thereby slowing the progression of cardiovascular diseases." (PMID 39175627, 2024). "Among the S100 family of binding proteins S100A8, S100A9, and S100A12 have been identified as DAMPs and linked with cardiovascular disease (CVD)." (PMID 38275751, 2023). "We were also able to demonstrate an association of CEBPD, and S100A8 and S100A9 expression in the context of human cardiovascular disease." (PMID 35543413, 2022). "Previously, the involvement of S100a8/a9 in autophagy and apoptosis was found in various tumors and other chronic inflammatory diseases, but that was rarely mentioned in cardiovascular diseases." (PMID 35741040, 2022). "S100A8 is a calcium- and zinc-binding protein that plays a prominent role in the regulation of inflammatory processes and immune responses including cardiovascular disease." (PMID 31941045, 2020). "S100A8/A9 has recently attracted an increasing amount of interest as a crucial alarmin that regulates the pathogenesis of cardiovascular disease after its release from myeloid cells." (PMID 33282877, 2020). "Previous studies have shown that S100 protein family members are involved in cardiovascular disease, such as S100B, S100A8, S100A9, and S100A12." (PMID 31275446, 2019). "Drugs targeting the S100A8/S100A9 complex leading to modulation of inflammatory response have been proposed in the treatment of cardiovascular disease." (PMID 26222498, 2015). "Despite functioning as a proinflammatory mediator, the pathophysiological roles of S100A8, S100A9, and S100A8/A9 complexes in cardiovascular disease are incompletely defined." (PMID 24595267, 2014). "S100A8, S100A9, and S100A12 are produced by cells of myeloid origin and have been linked with cardiovascular disease (CVD)." (PMID 24453429, 2013). "The dual nature of S100A8/A9 complicates its role in cardiovascular disease." (PMID 40948795, 2025). "Currently, there is a consensus that S100A8/A9 holds promise as a biomarker for cardiovascular diseases (CVDs), exerting an influence on cardiomyocytes or the cardiovascular system through multifaceted mechanisms that contribute to myocardial injury or dysfunction." (PMID 39329929, 2024).
cardiovascular disease (continued). "Thus, blocking S100A8/A9 in an appropriate therapeutic window may be a viable strategy to improve the prognosis of patients with cardiovascular disease." (PMID 39329929, 2024). "Thus, S100A8/A9 might represent a useful biomarker and therapeutic target in cardiovascular disease." (PMID 24453429, 2013). "But the pathophysiological roles of S100A8, S100A9 and S100A8/A9 in cardiovascular diseases are incompletely explained." (PMID 24595267, 2014). "The involvement of S100A8 and S100A9, DAMPs belonging to the S100 calgranulin family, in the pathogenesis of cardiovascular disease is attracting an increasing amount of interest." (PMID 24453429, 2013). "To date, no clinical trials have investigated targeted inhibition of S100A8/A9 in cardiovascular diseases, underscoring the need to assess the safety and efficacy of S100A8/A9 inhibitors in phase 2 trials." (PMID 40948795, 2025). "However, there are no studies comparing the roles of S100A8/A9 in different cardiovascular diseases cross-sectionally or longitudinally at different stages of the same disease." (PMID 39329929, 2024). "Thus, S100A8 and S100A9 might serve as a useful biomarker and therapeutic target in human cardiovascular disease; besides, S100A8 and S100A9 blockers have been developed and are approved for clinical testing." (PMID 30886860, 2019). "In addition, the S100A8 concentrations in serum and saliva showed significant differences according to the organ damage and were similar to the results of comparing the differences in S100 proteins depending on the presence of SDI scores in SLE patients with cardiovascular disease." (PMID 35529863, 2022).
inflammation (30 papers, 2011 to 2025). Aberrant reaction of the microcirculation characterized by movement of fluid and leukocytes from the blood into extravascular tissues. "Another study found that in mice exposed to mechanical ventilation/LPS injury, S100A8/A9 deficiency saved mice from lung inflammation, as seen by decreased alveolar-epithelial permeability, low neutrophil influx, and less cytokine/chemokine release in BAL of S100A9 KO mice compared to WT mice." (PMID 29180999, 2017). "This study demonstrates the role of S100A8/A9 during platelet–neutrophil interactions and neutrophil recruitment during pulmonary inflammation." (PMID 36497202, 2022). "It has been supported that knockout of RAGE demonstrated a protective effect from mainstream cigarette smoke-induced airway inflammation in mice, possibly via downregulating S100A8/A9 expression and amplifying immune-inflammatory responses." (PMID 33567747, 2021). "Here, we report the role of S100A8 in anterior ocular inflammation and the effect of glucocorticoids and NF-kB inhibitors on S100A8 expression." (PMID 27786310, 2016). "To evaluate if TLR4 signaling was required for S100A8/A9-induced aggravation of VILI we analyzed pulmonary inflammation in TLR4 mutant mice." (PMID 23874727, 2013). "These experiments suggest that when pulmonary S100A8/A9 or S100A8 levels are highly increased, these proteins have additive effects in overinflated lung areas in enhancing pulmonary inflammation." (PMID 23874727, 2013). "Consistent with previous mouse studies, genes associated with epidermal inflammation (e.g., IL-6, IL1B, S100A7, S100A8, and S100A9) and matrix metalloproteases (MMPs) were also significantly upregulated, as were E- and L-selectin, which are required for leukocyte entry into skin." (PMID 41150413, 2025). "S100A8 might represent a potential therapeutic target for treating neutrophilic lung inflammation in conditions where glucocorticosteroid responses are suboptimal." (PMID 33567747, 2021). "It has been proposed that the transition from the chronic intestinal inflammation to CRC involves changes in ECM matrix proteins, such as FN, matrix regulators like serpin H1, and matrix enzymes and inflammatory factors, such as S100A8 and S100A9." (PMID 39195201, 2024). "The aim of this study was the investigation of the role of S100A8/A9 proteins in PNC formation, neutrophil recruitment and the fate of pulmonary inflammation in murine models of inflammation in vivo and in vitro." (PMID 36497202, 2022). "Caloprotectin, a heterodimeric complex of S100A8 and S100A9, is known as anti-microbial in human skin and highly expressed during chronic inflammation with compromised barrier function in skin." (PMID 27556734, 2016). "S100A8, S100A9, and S100A12 were supposed to directly stimulate the production of mucin 5AC (MUC5AC), a major mucin protein in the airway which closely correlated with airway inflammation." (PMID 35348596, 2022).
bacterial infection (26 papers, 2009 to 2025). "SAP levels have been associated with the innate immunity of the host against bacterial infection, while S100A8/A9 proteins mediate neutrophil accumulation in TB inflammatory granulomas, serving as potential biomarkers for TB severity." (PMID 40370442, 2025). "Several studies demonstrated that S100A8/A9 affects the outcome of bacterial infections." (PMID 36497202, 2022). "S100A8/9 and IL5 were the most significantly increased and decreased proteins, respectively, in the bacterial infection category." (PMID 37831367, 2024). "However, there was no noticeable difference in S100A8/A9 levels between patients with G- and G+ bacterial infections (P > 0.5)." (PMID 40568710, 2025).
infectious disease (12 papers, 2014 to 2025). A disorder directly resulting from the presence and activity of a microbial, viral, or parasitic agent in humans. "Previous reports have shown that S100A8 is associated with many infectious diseases and strongly induces neutrophils recruitment." (PMID 34784362, 2021). "A variety of inflammatory cells (such as classical monocytes and granulocytes) displayed overexpression of S100A8/A9, and increased serum levels of these molecules have been observed in other infectious diseases (e.g., COVID‐19)." (PMID 39135683, 2024). "Therefore, we conclude that S100A8/A9 is induced in two infectious diseases studied here and may play a modulatory role in acute infection caused by bacteria and protozoa." (PMID 37831367, 2024). "At present, S100A8, S100A9, and S100A12 proteins generated from human or mouse sources have been extensively studied and proven to be powerful in the prevention and treatment of infectious diseases." (PMID 38256103, 2024). "S100A8, S100A9, and S100A12 proteins are important members of the S100 protein family, act primarily as congenital immunomodulators, and are closely related to the occurrence of infectious diseases." (PMID 38256103, 2024). "The aim of this study was to evaluate whether routine C-reactive protein (CRP) and additional inflammatory parameters myeloid-related protein 8/14 (MRP8/14 or S100A8/9) and human neutrophil-derived elastase (HNE) could distinguish KD from infectious diseases." (PMID 32775314, 2020). "And serum levels of S100A8/9 and S100A12 are also elevated in SLE and infectious disease." (PMID 30687316, 2018).
hematological malignancies (10 papers, 2013 to 2023). "Accumulating evidence showed that S100A8 and S100A9 play pathogenic and prognostic roles in solid cancer types and hematological malignancies." (PMID 37691822, 2023). "The prognostic role of S100A8 has mainly been demonstrated in hematological malignancies." (PMID 30456203, 2018).
immune disease (9 papers, 2014 to 2025). "Two recent studies have reported that SARS-CoV-2 infection can induce S100A8/A9, an endogenous toll-like receptor 4 ligand, which caused a neutrophil-mediated immune disorder 21,22." (PMID 35874943, 2022). "The analysis revealed the significant enrichment of genes such as HLA-DQB1, HLA-DPA1, S100A8, SFRP1, CD247, CTSH, and LAMP3, which are linked to inflammatory and immune disease pathways." (PMID 40426861, 2025). "We show S100A8/A9-associated functional enrichment categories included “neutrophil degranulation”, “innate immune system”, “immune system”, “regulation of TLR by endogenous ligand”, and “diseases of the immune system”." (PMID 36914713, 2023). "S100a8, a member of the S100 family, is involved in inflammatory responses and immune diseases." (PMID 35907209, 2022).
gastrointestinal neoplasms (8 papers, 2009 to 2025). "Indeed in vivo studies with S100a9-/- animals highlighted a crucial role for S100a8/a9 in the promotion of inflammation and inflammation-induced carcinogenesis in models of antigen-induced arthritis and colon carcinogenesis, respectively." (PMID 23241281, 2012).
lung (8 papers, 2016 to 2025). "We used this antibody to demonstrate that the functional blockage of S100A8/A9 ameliorates lung IR injury." (PMID 36354584, 2022). "As expected, anti-S100A8/A9 antibody significantly reduced plasma S100A8/A9 levels, thereby ameliorating lung IR injury." (PMID 36354584, 2022). "Inhibition of S100A8 and S100A9 by neutralizing antibodies also attenuated lung neutrophilia in a model of serotype 3 IPD, surprisingly without affecting bacterial clearance or survival of mice." (PMID 37467233, 2023).
neurodegenerative disease (8 papers, 2021 to 2025). A disorder of the central nervous system characterized by gradual and progressive loss of neural tissue and neurologic function. "Overall, our results present a mechanisticbasis for understanding the molecular interactions between S100A8and the plasma membrane, emphasizing S100A8 as a potential contributorto the onset of neurodegenerative diseases." (PMID 39723944, 2025). "Recent research has highlighted the roleof S100A8 in the progression of neurodegenerative diseases;12,13 however, the involvement of the plasma membrane in this processremains unclear." (PMID 39723944, 2025). "In the CNS, S100A8 is related to neurodegenerative diseases such as AD, where the expression of S100A8 is twofold higher in the hippocampi of AD patients compared to that of non-demented cases." (PMID 34449045, 2021). "The identified hub genes—particularly MMP9, CCL2, and S100A8/A9—may serve as promising candidates for therapeutic intervention or biomarker development across multiple neurodegenerative diseases." (PMID 41614741, 2025). "Our study reveals a novel relationship between S100A8/A9 and DUBs in neurodegenerative diseases." (PMID 38780644, 2024). "Moreover, sinceS100A1 is expressed constantly and S100A8 expression increases during neuroinflammation, the aggregation of proteins could only occurduring neurodegenerative disease onset or progression." (PMID 40560667, 2025).